PKD2 (polycystin 2, transient receptor potential cation channel)
Diseases named in the same sentence as PKD2 in open-access papers (continued):
Sharing a sentence is not in itself a finding about the gene and the disease.
cyst (continued). "They observed a time-dependent effect of tolvaptan treatment on cyst size only in PKD1−/− and PKD2−/− tubuloids that were derived from a distinct subpopulation of CD24+ human kidney cells, which are hypothesized to represent an adult renal stem/progenitor population." (PMID 36831216, 2023). "Our findings indicate that Pkd2 deletion activates JNK signaling and could drive cyst formation." (PMID 34962918, 2021). "Additionally, PKD1 patients present with more severe cysts than PKD2; however, this is likely due to development of cysts at an earlier age rather than an increase in cyst growth." (PMID 29479522, 2017). "In addition, Oc-Cre;Pkd2flox/null, and Oc-Cre;Pkd2flox/+ demonstrated no cyst formation in the kidney, consistent with the bone specific inactivation of Pkd2 (data not shown)." (PMID 25464512, 2014). "However, miR-182-5p inhibition could not slow cyst growth in Pkd2f/f:Aqp2-cre mice because Wasf2, Dock1, and Itga4 play significant roles in Pkd1 but not in Pkd2 conditional KO mice." (PMID 29074972, 2017). "Screening of 247 protein kinase inhibitors in a live imaging assay identified UCN-01, UCN-02, I κ B kinase (IKK) inhibitor VII, and quinazoline as inhibiting cyst formation in PKD1−/− and PKD2−/− kidney organoids without adversely affecting organoid growth." (PMID 37146581, 2023). "It is tempting to speculate that at least some of the PKD2 mutations observed in ADPKD patients do not completely abolish the function of polycystin-2 but rather alter its ion channel properties, thereby inducing cyst formation to an extent similar to that observed in our mouse model." (PMID 34345895, 2021).
polycystic kidney disease (119 papers, 2008 to 2026). A usually autosomal dominant and less frequently autosomal recessive genetic disorder characterized by the presence of numerous cysts in the kidneys leading to end-stage renal failure. "On the genetic front, hundreds of gene variants can cause or drive the progression of CKD, such as variations in the PKD1 and PKD2 genes in patients with polycystic kidney disease, and COL4A5 gene variants in those with Alport syndrome." (PMID 41598767, 2026). "We first used in vitro spheroidgenesis analysis for Pkd2-mutated mIMCD3 cells as a three-dimensional culture model of polycystic kidney disease." (PMID 39900437, 2025). "The TSC2 gene is in close proximity to the PKD2 gene on chromosome 16, which causes the autosomal dominant form of polycystic kidney disease, potentially leading to a contiguous gene deletion syndrome." (PMID 40141713, 2025). "The causes of polycystic kidney disease due to PKD2 mutation can currently be categorized into three main aspects." (PMID 39451240, 2024). "In one study, the author reported on a family carrying a mutation in the PKD2 gene perinatal death due to polycystic kidney disease occurred in the mother’s second and third pregnancies." (PMID 38318287, 2023). "It is interesting to note that the same individual was also identified with a heterozygous pathogenic variant in PKD2 gene c.637C > T p.Arg213Ter associated with AD polycystic kidney disease explaining the renal phenotype." (PMID 35123515, 2022). "Polycystic kidney disease is one of the most com-mon inherited kidney diseases.It is caused by mu-tation in either PKD1 or PKD2 genes, of which PKD1 ac-counts for 85%of the cases." (PMID 39077603, 2022). "It is curious that kidney cysts in Pkd2poreL1/poreL1 mice developed on a 129/Sv and not on a C57Bl/6 background, indicating that modifying effects are of great importance when polycystic kidney disease results from a mutation in the Pkd2 gene." (PMID 34345895, 2021). "Those small CNVs are the focus of MLPA analyses, which can be developed specifically for exons of genes known to be often affected by deletions/duplications, such as PKD1 or PKD2, causative of polycystic kidney disease." (PMID 34573409, 2021). "Genes PKD1 and PKD2 encode polycystin 1 (PC1) and polycystin 2 (PC2), respectively, that are responsible for ADPKD; yet, the biological function of polycystins remains elusive and controversial." (PMID 33013483, 2020). "The Consortium of Radiologic Imaging Studies of the Polycystic Kidney Disease (CRISP) cohort revealed that 89.1% had either a PKD1 or PKD2 mutation." (PMID 31488014, 2019). "In fact, the cysts that characterize polycystic kidney disease have been observed in kidney organoids derived from human pluripotent stem cells with CRISPR-Cas9-mutated PKD1 or PKD2 genes." (PMID 30379927, 2018). "We newly identified the regulation of miR-372-3p on PKD1/PKD2, indicating the possible association of miR-372-3p with polycystic kidney disease for the first time." (PMID 29941943, 2018). "Mutations in the gene for polycystin 2 (Pkd2) lead to polycystic kidney disease, however the main cause of mortality in humans is cardiac related." (PMID 27081851, 2016). "Abnormal expression of PKD2 in patients with polycystic kidney disease has been associated with a range of vascular abnormalities including BAV morphology, intracranial aneurysms, dilatation of the aortic root and dissection of the thoracic aorta." (PMID 22903503, 2013). "Polycystic kidney disease is caused by mutations in either PKD1 or PKD2." (PMID 39982357, 2025). "ADPKD is primarily caused by mutations in the polycystic kidney disease genes 1 or 2 (PKD1 or PKD2), and less commonly by variants in other genes such as glucosidase II alpha subunit (GANAB), which have been associated with milder renal phenotypes and concurrent polycystic liver disease." (PMID 41181723, 2025).
polycystic kidney disease (continued). "However, numerous models have been proposed to elucidate the pathogenesis of ADPKD and the mechanisms by which mutations in the PKD1 and PKD2 genes lead to the development of polycystic kidneys." (PMID 38891834, 2024). "Next-generation sequencing (NGS)-based analysis of polycystic kidney disease (PKD)-associated genes in the proband revealed the presence of a pathogenic PKD2 variant and a likely pathogenic variant in PKD1, according to the American College of Medical Genetics and Genomics (ACMG) criteria." (PMID 37628640, 2023). "Finally, a truncating PKD2 variant co-segregating with polycystic kidney disease in the family allowed presymptomatic disease diagnosis." (PMID 35627274, 2022). "In fact, a suggestive local interaction pair of rs2725227 and rs2725222 (distance = 14 kb, Pint was 1.2E−05 in ARIC and 9.6E−03 in FHS) was near ABCG2, with both SNPs were located in PKD2, a candidate causal locus of polycystic kidney disease and regulator of SUA levels." (PMID 24821702, 2014). "Mutations in PKD1 and PKD2 genes are responsible for the development of polycystic kidney disease." (PMID 23997766, 2013). "The Mayo/Polycystic Kidney Disease Foundation variant database, a research tool, is the best current database of PKD1 and PKD2 variants containing over 2300 variants identified in individuals with polycystic kidney disease, but novel variants are often identified." (PMID 37962562, 2024). "The three PKD2 mutations may have an important effect on the correct folding of this region of the polycystin domain, resulting in a hampered protein function that leads to polycystic kidney disease." (PMID 33268808, 2020). "Polycystic kidney disease (PKD), a ciliopathy caused primarily by mutations in the Pkd1 and Pkd2 genes, disrupts renal structure and function, leading to progressive renal failure." (PMID 40507782, 2025). "In ADPKD cohorts enriched for rapidly progressive disease, such as HALT Progression of Polycystic Kidney Disease (HALT-PKD) study and Consortium for Radiologic Imaging Study of PKD, PKD1 and PKD2 variants account for approximately 78% and 15% of cases." (PMID 37962562, 2024). "In 85% of cases where pathogenic genetic variants are found, ADPKD is the result of mutations in Polycystic Kidney Disease 1 (PKD1, OMIM #601313) (70% of cases) and Polycystic Kidney Disease 2 (PKD2, OMIM #613095) (30% of cases) genes." (PMID 39200828, 2024). "This is different from that in polycystic kidney disease, which is mainly caused by mutations of PKD1 or PKD2." (PMID 38433557, 2024). "The discovery that reintroducing the TRIC-B potassium channel can rescue kidney cysts offers a new perspective for identifying drug targets to treat PKD2-induced polycystic kidney disease." (PMID 39451240, 2024). "Polycystic kidney disease (PKD), which is most frequently associated with Autosomal Dominant PKD (ADPKD) due to PKD1 and PKD2 heterozygous variants, is emerging as a possible clinical manifestation in COL4A3-A5 patients." (PMID 38790225, 2024). "Polycystic kidney disease (PKD), a hallmark ciliopathy, is caused by mutations in the PKD1 and PKD2 genes which encode for the polycystin 1 (PC1), and 2- (PC2) proteins respectively." (PMID 36776558, 2023). "ADPKD is caused primarily by mutations in PKD1 or PKD2, which encodes polycystin-1 (PC1) or polycystin-2 (PC2), respectively (polycystins or PCs collectively)." (PMID 35832738, 2022). "The polycystic kidney disease (PKD) genes PKD1 and PKD2 code for polycystin 1 (PC1) and polycystin 2 (PC2), respectively, and are known as the causal genes of ADPKD." (PMID 34980882, 2022). "Our study demonstrates that TL was shortened and TERRA expression levels in the DNA-attached fraction increased in autosomal dominant polycystic kidney patients with mutations in PKD1 and PKD2 compared to the control group." (PMID 36291168, 2022).
polycystic kidney disease (continued). "ADPKD is mainly caused by mutations of polycystic kidney disease 1 (PKD1) and polycystic kidney disease 2 (PKD2), which encode for polcystin‐1 (PC‐1) and polycystin‐2 (PC‐2), respectively." (PMID 36540879, 2022). "We demonstrate the utility of this approach in embryos with polycystic kidneys (pkd1 and pkd2) and craniofacial dysmorphia (six1)." (PMID 34739029, 2021). "Analysis of mammalian and nematode EVs content has detected several proteins that were originally enriched in the cilia, in particular polycystic kidney disease (PKD) protein polycystin-2/PKD2." (PMID 34533135, 2021). "BICC1 is involved in osteoblastogenesis and polycystic kidney disease, in part, through its inhibition of posttranscriptional silencing of PKD2 RNA by miR‐17." (PMID 33977200, 2021). "As shown in the previous studies, expression of two ion transport proteins, Pkd2 (Polycystic kidney disease 2, TPM: 20.6) and Clcn4 (H+/Cl– exchange transporter 4, TPM: 9.5), were found in the current transcriptome." (PMID 34803745, 2021). "Conditional and kidney-specific ablation of Pkd2 results in penetrant and reproducible polycystic kidney phenotype in mice." (PMID 33199522, 2020). "The identification of renal eQTLs for genes involved in polycystic kidney disease (Pkd2, cis-effect, LOD=19, P<0.001; Pkdrej, trans-effect, LOD=4.88, P=0.0042) provides molecular evidence of the extent of renal anomalies in the GK rat." (PMID 31213483, 2019). "In the Consortium of Radiologic Imaging Studies of Polycystic Kidney Disease (CRISP) cohort, 89.1% had either a PKD1 or PKD2 mutation." (PMID 31488014, 2019). "With regard to Pkd2 mouse mutants, it was previously shown that somatic inactivation of Pkd2 expectedly resulted in polycystic kidney disease but also prenatal lethality and cardiac defects." (PMID 25589952, 2015). "Approximately 85% of cases are due to mutation in the polycystic kidney disease 1 gene (PKD1) in chromosome 16 and 15% to polycystic kidney disease 2 gene (PKD2) in chromosome 4." (PMID 23304619, 2012). "Consistent with the in vitro data set, the Pkd2 L515R mutant mice show polycystic kidney." (PMID 39900437, 2025). "The proportion of PKD1 or PKD2 pathogenic variants in patients without a positive family history of polycystic kidneys is low, and the presence of IFT140 pathogenic variants is significant." (PMID 39291187, 2024). "The effect of preprocessing on radiomic features was investigated using a single T2-weighted fat saturated (T2W-FS) MRI scan from PKD1 and PKD2 subjects (29 kidneys in total) from the Consortium for Radiologic Imaging Studies of Polycystic Kidney Disease study." (PMID 38156331, 2023). "In the 2000s, polycystin-1 and polycystin-2 proteins (mechanosensory complex), encoded by the causative genes PKD1 and PKD2 of polycystic kidney disease (PKD), a genetic disorder, gained attention due to their specific presence in the primary cilia of renal tubular epithelial cells." (PMID 37900915, 2023). "Indeed, brain ECs from a ciliopathic mouse (polycystic kidney disease or Pkd2−/−) also possess more than one cilium." (PMID 38028541, 2023). "The PKD2 gene, encoding polycystin-2, is associated with polycystic kidney disease, and the clinical symptoms usually do not appear until adulthood, but the disease starts in utero." (PMID 38318287, 2023). "Polycystic Kidney Disease (PKD), which is attributable to mutations in the PKD1 and PKD2 genes encoding polycystin‐1 (PC1) and polycystin‐2 (PC2) respectively, shares common cellular defects with cancer, such as uncontrolled cell proliferation, abnormal differentiation and increased apoptosis." (PMID 31251475, 2019). "Using a combination of genetic complementation with deletion constructs and virus overlay assays with individual domains, we find that AAV2 functionally interacts predominantly with the second Ig-like polycystic kidney disease (PKD) repeat domain (PKD2) present in the ectodomain of AAVR." (PMID 28679762, 2017).
polycystic kidney disease (continued). "To determine whether the changes in Glis2 expression found in Pkd1 models are extensible to other preclinical models of ADPKD, we used a mouse model in which polycystic kidney disease resulting from inactivation of Pkd2 is rapidly reversed by re-expression of Pkd236." (PMID 38693102, 2024). "In addition, neither single Pkd1 and Kif3a nor double Pkd1 and Kif3a mutant mice developed polycystic kidney disease, unlike the reported additive effects of Pkd1 and Pkd2 deficiency to enhance renal cyst formation." (PMID 21151991, 2010). "We identified five homologs of polycystic kidney disease (PKD): PKD1-1, PKD1-2, PKD1-3, PKD1-4, and, PKD2, from the P. naikaiensis genome." (PMID 38305882, 2024). "The AAVR contains five polycystic kidney disease (PKD) repeat domains, from which PKD2 is recognized by AAV1 and AAV2 87,88." (PMID 36977781, 2023). "For genetic workup, further polycystic kidney disease genes were analyzed, PKD1 and PKD2 in 12, HNF1B in 8, and DZIP1L and GANAB in 5 children each without detection of variants." (PMID 35812281, 2022). "First, we were interested in Pkd2, the S. pombe ortholog to the mammalian Transit Receptor Potential (TRP)-like polycystic-kidney-disease (PC2) ion channel." (PMID 34349749, 2021). "Full-length PrtV protein contains 918 amino acids and consists of one M6 peptidase domain, a zinc- binding domain, and two C-terminal Polycystic Kidney Disease domains (PKD1 and PKD2)." (PMID 26222047, 2015). "Both these molecules are involved in autosomal dominant polycystic kidney and liver diseases, and PRKCSH acts as a chaperone-like molecule to regulate PKD2 expression." (PMID 25528770, 2015). "Ultrasound sensitivity and specificity generally improved with age and were worse in PKD2 patients compared to PKD1 (lowest reported 31% and 88%, respectively, in polycystic kidney disease (PKD) 2 patients aged 5–14; highest 100% and 100%, respectively, in multiple gene/age categories)." (PMID 40697969, 2025). "In addition, miR-17 has been shown to downregulate polycystin-1 (PKD1) and polycystin-2 (PKD2), crucial for the mechanosensory function of primary cilia in polycystic kidney disease." (PMID 39268086, 2024). "Polycystic kidney disease (PKD) was ruled out by negative genetic testing of the causative genes PKD1 and PKD2." (PMID 37768732, 2023). "For a direct role in the transcription of PKD2 and PKHD1, HNF1β has been recognized as a modifier in PKD, although mutations in HNF1B do not cause typical polycystic kidney disease." (PMID 33809516, 2021). "Compared to non-cystic control kidneys, polycystic kidneys of PBS-treated Pkd2-KO mice exhibit an age-dependent progressive decline in miR-17 PD-Sig, indicative of increasing miR-17 activity with disease progression." (PMID 31515477, 2019). "Here, we demonstrate that the PC2 L517R mutation located at this site does not significantly impair the channel activity despite the lack of cholesterol binding and that Pkd2 L515R mutant mice show disrupted left–right asymmetry determination and polycystic kidney." (PMID 39900437, 2025). "The causes of atypical polycystic kidney disease by imaging are heterogeneous and may include somatic mosaicism, mild disease associated with PKD1 non-truncating or PKD2 mutations, as well as mutations in other cystic disease genes." (PMID 36807559, 2023). "Furthermore, zebrafish pkd1b or pkd2 mutants did not display polycystic kidney during the larval stage." (PMID 38086423, 2023). "The gene responsible for the 85% of the cases is the polycystic kidney disease 1 PKD1 gene located on the shorter arm of the 16th chromosome, and the other gene responsible for the rest of the cases is the polycystic kidney disease 2 PKD2 gene located on the longer arm of the 4th chromosome." (PMID 23840219, 2013).
polycystic kidney disease (continued). "The biological functions of C-terminal two putative polycystic kidney disease domains (PKD1 and PKD2) has not yet been fully investigated, although they have been suggested to be involved in protein-protein or protein-carbohydrate interaction." (PMID 26222047, 2015). "At the age of 51 years, several kidney cysts were detected, raising the suspicion of polycystic kidney disease, which was later excluded by next-generation sequencing genetic testing: negative for Polycystin 1 (PKD1), Polycystin 2 (PKD2), and Ciliary IPT domain-containing fibrocystin (PKHD1) genes." (PMID 40130200, 2025).